CLIC3 (CLIC family member 3)
Description:
In the soluble state, catalyzes glutaredoxin-like thiol disulfide exchange reactions with reduced glutathione as electron donor. Reduced in a glutathione-dependent way and secreted into the extracellular matrix where it activates TGM2 and promotes blood vessel growth during tissue remodeling as occurs in tumorigenesis. Can reduce specific cysteines in TGM2 and regulate cofactor binding. Can insert into membranes and form outwardly rectifying chloride ion channels. May participate in cellular growth control.
Tractability: Antibody: UniProt places it where antibodies can reach, with high confidence; its Gene Ontology location is reachable by antibodies, with high confidence; UniProt predicts a signal peptide or a membrane-spanning region. PROTAC: ubiquitination databases record sites on it; its protein half-life has been measured.
Gene: Protein-coding gene on chromosome 9 (136,994,608 to 136,996,568, reverse strand). Ensembl gene ENSG00000169583.
Subcellular location: Nucleus; Membrane; Cell membrane; Cytoplasm; Secreted, extracellular space, extracellular matrix
Subcellular location (Human Protein Atlas): Nuclear bodies
Gene Ontology:
Molecular function: chloride channel activity; protein binding; protein-disulfide reductase (glutathione) activity
Biological process: chloride transport; positive regulation of sprouting angiogenesis; signal transduction; chloride transmembrane transport
Cellular component: cytoplasm; extracellular exosome; extracellular matrix; nuclear body; nucleus; plasma membrane; membrane
Genetic constraint (gnomAD): Loss-of-function variants: 30 observed, 19.91 expected, observed/expected ratio (o/e) 1.51, 90% interval 1.12 to 1.9. The upper end of that interval is the gene's LOEUF score, 1.9, which puts it in group 6 of 6, group 1 being the genes least tolerant of losing a copy. Missense variants: 365 observed, 304.64 expected, observed/expected ratio (o/e) 1.2, 90% interval 1.1 to 1.31. Synonymous variants: 143 observed, 133.91 expected, observed/expected ratio (o/e) 1.07, 90% interval 0.93 to 1.23.
Homologues: Orthologues: chimpanzee CLIC3 (99% identical), macaque CLIC3 (98% identical), guinea pig CLIC3 (90% identical), mouse Clic3 (90% identical), dog CLIC3 (89% identical), pig CLIC3 (85% identical), rat Clic3 (77% identical), tropical clawed frog clic3 (58% identical), zebrafish clic3 (58% identical), Caenorhabditis elegans exl-1 (27% identical), Caenorhabditis elegans exc-4 (25% identical), Drosophila melanogaster Clic (23% identical), and 28 more. Paralogues in human: CLIC1 (52% identical), CLIC5 (51% identical), CLIC6 (50% identical), CLIC2 (50% identical), CLIC4 (50% identical), GSTT2 (20% identical), GSTT2B (20% identical), EEF1G (19% identical), GDAP1 (18% identical), GSTT4 (17% identical), GDAP1L1 (17% identical), GSTO2 (15% identical), and 2 more.
Diseases named in the same sentence as CLIC3 in open-access papers:
CLIC3 is named in the same sentence as 29 diseases in open-access papers, as found by Europe PMC text mining. Sharing a sentence is not in itself a finding about the gene and the disease. The quoted sentences say what the papers report.
breast carcinoma (9 papers, 2017 to 2025). "CLIC3 was found in the stroma surrounding fibroblasts associated with breast cancer, which is known to be in part secreted by breast cancer-associated fibroblasts." (PMID 32116799, 2020). "Similarly, CLIC3 levels have been shown to be elevated in 90% of ovarian cancer patients, where upregulation of CLIC3 in breast cancer tissue was associated with increased cancer cell invasiveness." (PMID 35223789, 2022). "Moreover, CLIC3 is associated with poor prognosis in pancreatic cancer, breast cancer, ovarian cancer, and malignant pleural mesothelioma." (PMID 32066374, 2020). "CLIC3 has been demonstrated to have a role in invasion and metastasis in breast cancer cell line, and the overexpression of CLIC3 in oestrogen receptor-negative predicts a poor prognosis." (PMID 34721733, 2021). "As a soluble protein, secreted CLIC3 promotes angiogenesis and invasion of ovarian cancer cells and breast cancer cells both in vivo and in 3D cell culture models by reducing transglutaminase-2." (PMID 32066374, 2020). "Chloride intracellular channel protein 3 (CLIC3) secreted by breast cancer CAFs induces angiogenesis through an active transglutaminase-2 (TGM2) mediated mechanism." (PMID 30380628, 2018). "Hence, the CLIC3/TGM2 pathway promotes angiogenesis in vivo, and breast cancer invasion in 3D culture and in vivo." (PMID 28198360, 2017).
ovarian carcinoma (8 papers, 2012 to 2025). A malignant neoplasm originating from the surface ovarian epithelium. "Preliminary tissue microarray analysis demonstrates strong CLIC3 staining in the stroma of highly vascularized ovarian cancers, further supporting its association with tumor aggressiveness." (PMID 41465326, 2025). "Taken together, these data indicate that high CLIC3 levels in aggressive ovarian cancers are associated with poor patient outcomes." (PMID 28198360, 2017). "Furthermore, high CLIC3 expression is associated with increased resistance to cisplatin in ovarian cancer (OC), which is mechanistically underpinned by enhanced integrin β1 redistribution and activation of the PI3K-AKT pathway, thereby contributing to chemoresistance and metastatic competence." (PMID 41465326, 2025). "Elevated levels of CLIC3 in ovarian cancer tissue, both in the tumor cell and stromal compartments, correlate with poor clinical outcomes." (PMID 41465326, 2025). "Finally, CLIC3 is also secreted by cancer cells, is abundant in the stromal and tumour compartments of aggressive ovarian cancers and its levels correlate with poor clinical outcome." (PMID 28198360, 2017). "Rab25 and CLIC3 levels correlated with one another in both pancreatic and ovarian carcinoma." (PMID 22197222, 2012). "A multivariate analysis revealed that, after controlling for TGFB2 expression, four genes (CLIC3, ANPEP/LAP1, RIN2, and EMP1) showed negative correlations between mRNA expression and OS across all expression levels in an ovarian cancer cohort." (PMID 41465326, 2025).
pancreatic cancer (8 papers, 2012 to 2026). "Pancreatic cancer patients with high Rab25 and high CLIC3 levels were associated with significantly shorter survival time." (PMID 28969096, 2017). "CLIC3 acts as a key regulator of cell migration in tissues and as an independent prognostic indicator in pancreatic cancer." (PMID 31212896, 2019). "A related molecule, regulator of integrin recycling, the CLIC3 intracellular chloride channel which drives invasiveness of pancreatic cancer is also upregulated in “short” survivors in the current study." (PMID 29515771, 2018). "Given the histological and pathophysiological similarities between ovarian and pancreatic cancers, we analyzed CLIC3 expression in neoplastic lesions of the human pancreas." (PMID 22197222, 2012). "Indeed, although the correlation between Rab25 and CLIC3 in pancreatic tumors is highly statistically significant, this relationship is not hard and fast, and there are many tumors that express Rab25 that do not express CLIC3 and vice versa." (PMID 22197222, 2012). "Moreover, CLIC3 expression was highly enriched in regions where the tumors were invading normal tissue, suggesting a role for CLIC3 in the invasive/metastatic behavior of pancreatic cancer." (PMID 22197222, 2012). "In pancreatic cancer, Rab25 acts as an oncogene in the presence of CLIC3, whereas, Rab25 acts as a tumor suppressor in the absence of CLIC3." (PMID 28969096, 2017). "Analysis of tissue microarrays (TMAs) that we have previously stained for CLIC3 (refs 30, 31) indicated that 90% of ovarian, 20% of breast and almost none of the pancreatic cancers stained positively for CLIC3 in the stroma." (PMID 28198360, 2017).
bladder cancer (6 papers, 2020 to 2025). "More recently, high expression of CLIC3 is associated with the poor clinicopathological factors and poor prognosis of bladder cancer patients." (PMID 38182571, 2024). "Kaplan–Meier survival analysis revealed that high expression of CLIC3 was remarkably associated with poor prognosis in bladder cancer patients." (PMID 38182571, 2024). "CLIC3 promoted the proliferation of bladder cancer cells by reducing p21 expression in vitro and in vivo." (PMID 38182571, 2024). "In summary, these results demonstrated that CLIC3 was a key gene in bladder cancer, which was mainly localized in the nucleus and was significantly upregulated in bladder cancer." (PMID 38182571, 2024). "In this study, we identified the TFCRs by integrating chromatin accessibility data of ATAC-seq and DNase-seq with TF motif, and discovered that CLIC3 was upregulated in bladder cancer tissues." (PMID 38182571, 2024). "Clinically, CLIC3 expression was significantly elevated in bladder cancer and was negatively correlated with patient survival." (PMID 38182571, 2024). "Meanwhile, inhibition of p21 expression rescued the G0/G1 cell cycle arrest, and attenuated the inhibition of colony formation ability upon knockdown of CLIC3 in bladder cancer cells." (PMID 38182571, 2024). "Consistent with those identified in TCGA database, CLIC3 was significantly upregulated in bladder cancer tissues." (PMID 38182571, 2024). "Nevertheless, more in-depth research is still needed to investigate the role of CLIC3 in regulating cell metastasis and the sensitivity of therapy in bladder cancer." (PMID 38182571, 2024). "To further confirm the clinical role of CLIC3 in bladder cancer, we analyzed 86 pairs of bladder cancer and paired normal bladder tissues." (PMID 38182571, 2024). "Consistent with our RNA-seq results, knockdown of CLIC3 markedly increased p21 expression and CLIC3 expression was inversely correlated with p21 expression in bladder cancer tissues." (PMID 38182571, 2024). "Subsequently, we observed that knockdown of CLIC3 attenuated cell viability, colony formation ability and cell proliferation of bladder cancer cells." (PMID 38182571, 2024). "CLIC3 is highly expressed in bladder cancer and is a marker of poor prognosis in patients with bladder cancer." (PMID 36685927, 2022). "Although there is currently a bioinformation-based study on the role of CLIC3 in bladder cancer, the study only conducted a simple expression difference analysis and clinical correlation of CLIC3." (PMID 34721733, 2021). "Notably, CLIC3 was identified as a key gene in bladder cancer based on the correlation between gene expression and overall survival." (PMID 38182571, 2024). "As we expected, ectopic expression of CLIC3 promoted the proliferation of bladder cancer cells." (PMID 38182571, 2024). "Collectively, we proposed a TFCR-based framework to screen for key genes in bladder cancer, and revealed that CLIC3 could be a regulatory factor of NAT10-catalyzed ac4C modification, elucidating a novel mechanism for mRNA ac4C modification." (PMID 38182571, 2024). "Furthermore, CLIC3 was expressed at a high level in bladder cancer cells compared to normal urothelial cell SV-HUC-1, especially in J82 and TCCSUP." (PMID 38182571, 2024). "Overall, these findings uncover an novel mechanism of mRNA ac4C modification and CLIC3 may act as a potential therapeutic target for bladder cancer." (PMID 38182571, 2024). "Collectively, these results impiled that CLIC3 exerted pro-carcinogenic roles in bladder cancer." (PMID 38182571, 2024). "To confirm whether the effects of CLIC3 on cell proliferation were mediated via p21, we knocked down p21 in CLIC3-knockdown bladder cancer cells." (PMID 38182571, 2024). "Meanwhile, overexpression of CLIC3 also promoted the proliferation of bladder cancer cells in vivo." (PMID 38182571, 2024). "Remarkably, our study reveals that CLIC3 may act as a potential therapeutic target for curative management of bladder cancer." (PMID 38182571, 2024).
bladder cancer (continued). "Human intracellular chloride channel 3 (CLIC3) is involved in the development of various cancers, but the expression and prognostic value of CLIC3 mRNA in bladder cancer (BC) remain unclear." (PMID 31934512, 2020). "Functionally, CLIC3 could promote the proliferation of bladder cancer cells in vitro and in vivo." (PMID 38182571, 2024). "Chloride intracellular channel 3 (CLIC3) interacts with NAT10 and inhibits its function to promote bladder cancer progression, resulting in the downregulation of ac4C modification and the stability of p21 mRNA." (PMID 41316475, 2025). "CLIC3 interacts with NAT10 to inhibit NAT10‐mediated ac4C modification of p21 mRNA, thereby promoting bladder cancer progression." (PMID 39640362, 2024). "Therefore, CLIC3 might act as a promising therapeutic target in bladder cancer." (PMID 38182571, 2024). "However, the role and mechanism of CLIC3 in regulation of bladder cancer still remain unclear." (PMID 38182571, 2024). "Importantly, CLIC3 expressed at a high level in J82 and TCCSUP compared with other bladder cancer cells, including UMUC3 and T24." (PMID 38182571, 2024). "To investigate whether the effects of CLIC3 on ac4C modification of p21 mRNA were mediated via NAT10, we constructed a stable model of CLIC3 over-expressed in NAT10-knockdown bladder cancer cells." (PMID 38182571, 2024). "In general, CLIC3 could interact with NAT10 in the nucleus, where it inhibited NAT10-mediated ac4C modification of p21 mRNA, and promote cell growth in bladder cancer." (PMID 38182571, 2024). "Furthermore, CLIC3 and NAT10 were colocalized in the nuclear of bladder cancer cells." (PMID 38182571, 2024). "However, we demonstrated that CLIC3, mainly located in the nucleus, could interact with NAT10, but not with Rab25, to promote cell proliferation in bladder cancer." (PMID 38182571, 2024).
ovarian tumors (4 papers, 2012 to 2025). "PPI analysis showed that CLIC3 was associated with VSIG4 which is overexpressed in ovarian tumors exhibiting with progression and recurrence of the cancer." (PMID 41465326, 2025). "However, Rab25 is associated with elevated CLIC3 in both cultured A2780 cells and in pancreatic and ovarian tumors, and CLIC3 functions to return lysosomally targeted α5β1 to the plasma membrane, thus opposing receptor degradation." (PMID 22197222, 2012). "CLIC3 is also highly expressed in the stroma of aggressive ovarian tumors and is a prominent component of the CAF secretome." (PMID 41465326, 2025). "Histoscore analysis indicated that CLIC3 protein levels were higher in type II than in type I ovarian tumors, supporting a potential role for this protein in cancer invasion." (PMID 22197222, 2012). "We detected CLIC3 expression in various types of ovarian tumors including serous, endometrioid, clear cell, and mucinous carcinoma (data not shown) primarily in punctate cytoplasmic structures but also within the nucleus of some tumors." (PMID 22197222, 2012). "Immunohistochemistry staining indicated that CLIC3 was expressed in the stroma of ovarian tumours but not in the stroma of the corresponding normal tissue (uterus)." (PMID 28198360, 2017).
pancreatic ductal adenocarcinoma (4 papers, 2012 to 2024). An infiltrating adenocarcinoma that arises from the epithelial cells of the pancreas. "Meanwhile, CLIC3 and Rab25 collaborate to promote aggressiveness of pancreatic ductal adenocarcinoma through recycling integrin." (PMID 38182571, 2024). "CLIC3 was highly expressed in pancreatic ductal adenocarcinoma (PDAC), being localized to cytoplasmic granules but also observable in the nucleus of some cancers with high CLIC3 levels." (PMID 22197222, 2012). "CLIC3 expression predicts lymph node metastasis and poor prognosis in operable cases of pancreatic ductal adenocarcinoma (PDAC)." (PMID 22197222, 2012). "Besides, previous studies report that CLIC3 colocalizes with Rab25 and integrin in late endosomes/lysosomes to promote the migration and invasion of pancreatic ductal adenocarcinoma." (PMID 38182571, 2024).
gastric cancer (3 papers, 2016 to 2024). A primary or metastatic malignant neoplasm involving the stomach. "In the tissue microarray analysis using 107 gastric cancer specimens, CLIC3 expression was negatively correlated with pathological tumor depth, and the patients with lower expression of CLIC3 exhibited poorer prognosis." (PMID 32066374, 2020). "In the present study, we therefore investigated expression and function of CLIC3 protein in human gastric cancer cells." (PMID 32066374, 2020). "On the other hand, the proliferation was attenuated by exogenous CLIC3 expression in human gastric cancer cells (KATOIII and NUGC-4) in which endogenous CLIC3 expression is negligible." (PMID 32066374, 2020). "Future study is necessary to clarify the mechanism of regulation of CLIC3 expression in gastric cancer cells." (PMID 32066374, 2020). "Here, we also found that CLIC3 was partially expressed in the plasma membrane of gastric cancer cells in CLIC3-high patients and MKN7 cells." (PMID 32066374, 2020). "In a TMA of gastric cancer (107 specimens) treated with the anti-CLIC3 antibody, significant expression of CLIC3 protein (“CLIC3-high”) was found in 49 specimens." (PMID 32066374, 2020). "In the present study, the TMA analysis of patients with gastric cancer who underwent a surgery showed that expression level of CLIC3 was negatively correlated with overall survival and disease-specific survival." (PMID 32066374, 2020). "Our study clarifies that CLIC3 has a channel activity in the plasma membrane of gastric cancer cells, and that decreased expression of CLIC3 results in unfavorable prognosis of gastric cancer patients via stimulation of the cancer cell proliferation." (PMID 32066374, 2020). "Our results suggest that CLIC3 functions as a Cl− channel in the plasma membrane of gastric cancer cells and that decreased expression of CLIC3 results in unfavorable prognosis of gastric cancer patients." (PMID 32066374, 2020). "Pathophysiological functions of chloride intracellular channel protein 3 (CLIC3) in human gastric cancer have been unclear." (PMID 32066374, 2020). "Knockdown of CLIC3 in human gastric cancer cells significantly accelerates cell proliferation." (PMID 39483475, 2024). "CLIC3 expression was also found in a human gastric cancer cell line (MKN7)." (PMID 32066374, 2020). "In gastric cancer MKN7 cells endogenously expressing CLIC3, similar Cl− currents were observed." (PMID 32066374, 2020). "Changes in expression level of CLIC3 in the plasma membrane may disrupt intracellular Cl− homeostasis in gastric cancer cells, resulting in the enhancement of cancer cell growth." (PMID 32066374, 2020). "Decreased expression of CLIC3 in gastric cancer may result in poor prognosis of the patients." (PMID 39483475, 2024). "Thus, the plasma membrane expression of gastric CLIC3 may explain why CLIC3 function in gastric cancers is different from other cancers." (PMID 32066374, 2020). "In the present study, however, migration and invasion of cancer cells are not affected by exogenous CLIC3 expression in the gastric cancer cells." (PMID 32066374, 2020).
lymph node metastasis (3 papers, 2012 to 2020). "On the other hand, CLIC3 expression was not significantly related to gender, age, lymph node metastasis, liver metastasis, peritoneal dissemination, distant metastasis, peritoneal lavage cytology, pathological stage, histology, lymphatic invasion, and venous invasion." (PMID 32066374, 2020).